ITGB4 (integrin subunit beta 4)
Diseases named in the same sentence as ITGB4 in open-access papers (continued):
Sharing a sentence is not in itself a finding about the gene and the disease.
tumor (continued). "However, our studies also demonstrate that the transcription factor Fra-2 is able to control the expression of other adhesion molecules as well (L1-CAM, ICAM-1, CD44, ITGB4, and TSPAN8) and thus allows the tumour cells to adhere to the selectin-deficient endothelium via these adhesion molecules." (PMID 34693476, 2022). "ITGB4-targeted therapy might represent a resort to Cetuximab resistance using either antagonizing antibodies as presented here or immunomodulatory approaches including ITGB4-primed dendritic cells or bispecific antibodies targeting T cells and ITGB4-positive tumor cells." (PMID 36076232, 2022). "Differing localization of ITGB4 was observed within tumor areas including an exclusive expression at the interface between tumor and non-malignant stromal tissue, a marginal expression at the edges of tumor areas, and a more homogeneous expression throughout tumor cells." (PMID 36076232, 2022). "Functionally, we established via cytotoxicity, serum binding, and complement assays that ITGB4-DC vaccination, combined with anti-PD-L1 immunotherapy, induced cytotoxic splenic T cells and serum antibodies capable of mediating the binding and killing of both bulk tumor cells and ALDHhigh CSCs." (PMID 34504657, 2021). "Furthermore, it is reported that ITGB4 could promote the invasion and metastasis of tumor cells through a series of processes." (PMID 31875161, 2019). "In addition, EGFR, Mucin-1 (MUC1), and integrin beta-4 (ITGB4), which promote tumor growth and metastasis, may be bad prognostic factors in this tumor." (PMID 29282096, 2017). "Strikingly, only three genes—ITGB4, LDHA, and TIMP1—demonstrated significantly higher expression in tumor epithelial cells compared to their normal counterparts." (PMID 41187171, 2025). "While canonical EMT is well-studied in cancer progression, the hEMT state—marked by co-expression of epithelial (e.g., CDH1, IRF6, JUP) and mesenchymal (LAMC2, ITGB4, TGFA) genes—has emerged as a driver that enhances cellular plasticity and tumor metastasis." (PMID 40777467, 2025). "Strikingly, only three genes - ITGB4, LDHA, and TIMP1 – showed significantly elevated expression in tumor epithelial cells compared to their normal counterparts (P < 0.01)." (PMID 41187171, 2025). "This intricate interplay between ITGB4 and AKT highlights their critical roles in tumor cell migration and invasion." (PMID 39169946, 2024). "We confirmed the observed transcriptional upregulation of ITGB4 and the downregulation of ENPP1 and HMGCS1 in BMP4-expressing primary tumours at the protein level." (PMID 39273106, 2024). "The results revealed that the PI3K-AKT pathway was active in tumor cells and that MDFI upregulated the PI3K-AKT pathway by directly regulating LAMB3 and ITGB4." (PMID 38375821, 2024). "Their in vitro and in vivo study demonstrated a synergistic anti-tumor efficacy from the combination of carfilzomib and sotorasib in NSCLC cell lines and xenografts through downregulating ITGB4 and β-catenin expression." (PMID 38756650, 2024). "For instance, ITGB4 can interact with enzymes like 12-lipoxygenase (12-LOX), impacting tumor metastasis." (PMID 39169946, 2024). "Apart from SKP2, ITGB4, CDKN3, TFGP1, SLCO1B3, CDX2 and KIF18A, the remaining model genes showed significant correlations with stem cell score, immune score and tumour microenvironment." (PMID 39656479, 2024). "In this work, the data mining of PDAC scRNA-seq data revealed that ITGA2, ITGA3, ITGB4, and ITGB6 were dominantly expressed in tumor cells." (PMID 35719923, 2022). "Molecular characterization showed that ITGB4 was upregulated in primary tumors and metastases compared to normal mucosa and correlated with EGFR/MAPK activity in tumor bulk and single malignant cells." (PMID 36076232, 2022). "To validate ITGB4 targeting, we generated 4T1-ITGB4KO tumor cells and evaluated the specificity of our two ITGB4-directed treatment protocols." (PMID 34504657, 2021).
tumor (continued). "Previous research has found ITGB4 to be an independent predictor of survival and to be expressed in cells resembling CRC tumor‐budding cells." (PMID 34414684, 2021). "Among the integrin β‐subunits, ITGB1, ITGB2, ITGB4, ITGB5, ITGB6, ITGB7, and ITGB8 were highly expressed in tumour tissues compared with normal tissues." (PMID 34709754, 2021). "Meanwhile, the GEPIA database showed that JUP, ITGB4, ST3GAL2, ST3GAL5 and B4GALNT1 were higher expressed in tumor samples than in paired normal tissues." (PMID 34402716, 2021). "Interact with AQP2 to inhibit tumor growth and metastasis of HNSCC by regulating the actin cytoskeleton of SEPT2 and ITGB4." (PMID 34888249, 2021). "We also observed that CD70, ITGB4, and DCBLD2 were significant prognostic indicators in crosstalk and cell-cell communication between LUAD tumor cells and T cells." (PMID 32549766, 2020). "The violin plot showed the metastasis-related genes were higher expression in LUAD tumor tissues, but only LAMC2, THBS2, ITGB4, COL1A1 and FLNC showed positively correlated with poorer survival of LUAD and the expression level of GPR115." (PMID 33330053, 2020). "In the favorable ccrcc2_3 subtypes, miR-204-5p was strongly upregulated, predicted long OS, and repressed several targets that are involved in tumor invasiveness and metastasis (MMP3, MMP9, AURKB, FBN2, ITGB4, SPDEF)." (PMID 32915890, 2020). "The complex that consists of integrin subunit α6 (ITGA6) and subunit β4 (ITGB4) and sequentially interacts with laminin and kindlin-3 (FERMT3) is involved in tumorigenesis by modulating tumor cell–ECM interaction." (PMID 32326232, 2020). "Several key proteins such as MAP2K1, ITGB4, ITGA6, PTPN6, FMNL1, ANXA1, and MMP9 that modulate cell motility and tumor cell invasion were upregulated in MIBUC." (PMID 32326232, 2020). "We also performed a data-mining analysis to investigate the differences in the expression levels of ITGA11, ITGB4 and ITGB8 between tumor and normal tissues in NSCLC using GEO datasets." (PMID 31875161, 2019). "The results revealed that the expression levels of ITGA11, ITGB4 and ITGB8 were all significantly upregulated in tumor tissues compared with normal tissues." (PMID 31875161, 2019). "Consistent with the in vitro results, overexpression of miR-133b significantly restrained the tumor growth and lung metastases via regulating EGFR/ITGB4/FAK/Grb2 signaling pathway." (PMID 30479571, 2018). "The protein levels of EGFR, ITGB4 and p-FAK were increased in tumor tissues, as compared with in normal tissues." (PMID 30479571, 2018). "Intriguingly, some of these molecules are related to oncogenesis and tumour progression/metastasis, namely, HRAS, KRAS, TGFBR1, TGFBR2, RB1, ITGA6, ITGB4, mTOR, TSC2 and APLP2." (PMID 30258067, 2018). "Analysis of ITGB4 expression in HCC showed that it was expressed at higher levels in HCC tissues and cell lines than in adjacent non-tumor tissues and normal hepatic cells." (PMID 28084395, 2017). "The tumor sections from CuB treated mice showed reduced expression of HER2 and ITGB4 in MDA-MB-231 as well as 4T-1 tumor sections." (PMID 24729020, 2014). "Tumour and growth factor genes like WWOX, p73, ITGB4 and AREG were strongly up-regulated by PAR2 activation, supporting roles for PAR2 in proliferation, tumour growth and, perhaps surprisingly, also tumour suppression." (PMID 21072196, 2010). "Others are more distinctive of a "state", e.g. distribution of cytokeratins and down-regulation of certain integrins (ITGA6/ITGB4, ITGA7) in all the tumour-derived cell lines." (PMID 16626496, 2006).
tumor (continued). "Differential gene expression analysis demonstrated that Tum_1 tumor cells predominantly expressed basal cell marker genes such as KRT14, KRT5, and KRT15, and exhibited high levels of genes related to cell adhesion, including ITGB4 and ITGA6." (PMID 40470730, 2025). "Somewhat surprisingly, a low signal level of serum ITGB4–UEA, which demonstrated the highest signal levels among the serum assays, was associated with tumor recurrence, while the association was not confirmed in ROC analysis." (PMID 40287842, 2025). "Therefore, we used publicly available spatial transcriptomic (ST) data to interrogate sub-localizations of fDEGs in tumor core (TC), and leading edge (LE) of oral SCC (external dataset GSE208253), as exemplified for ITGB4, LAMA3, LAMB3, and LAMC2." (PMID 40121428, 2025). "Besides, the expression level of ITGB4 and ITGAV, integrin related to tumor metastasis, were also increased." (PMID 38724499, 2024). "Tumors lacking ITGB4 exhibit apoptosis and actively attract MDSCs, a cell population well known for its role in promoting tumor growth in various cancer types." (PMID 39432076, 2024). "Interestingly, ITGB4 can activate the PI3K/AKT pathway, further promoting the survival, proliferation, and migration of tumor cells." (PMID 38982076, 2024). "Evaluation of the differential gene expression revealed that only CTCs with ITGA6 and ITGB4 expression demonstrated increased expression of 14 tumor-progression related genes compared to the no integrins CTCs, almost half of which were related to EMT." (PMID 38250718, 2024). "ITGB4, functioning as a membrane receptor, when stimulated extracellularly, interacts with receptor tyrosine kinases, activating the downstream extracellular signal-regulated kinase (ERK) signaling pathway, thus facilitating tumor cell metastasis." (PMID 38733440, 2024). "Moreover, binding of PD-L1 to ITGB4 activates the AKT/GSK3β signaling pathway, thereby impacting the expression of the transcription inhibitor SNAIL and ultimately suppressing anti-tumor immunity." (PMID 39169946, 2024). "Treating tumor‐bearing mice with DNase I, to degrade NETs‐DNA, specifically blocked ITGB4 but not ITGB1‐driven metastatic colonization." (PMID 37828611, 2023). "More detailed ex vivo flow cytometric analyses of leukocyte subpopulations revealed an increased percentage of CD45+ CD11b+ Gr-1Hi SSCLo cells in the initial ITGB4 KD tumor nodules, whereas these changes were no longer evident in E-/P-selectin double KO mice." (PMID 36932441, 2023). "Furthermore, ITGB4 has been identified as a cancer stem cell (CSC) marker that operates by promoting metastasis, self-renewal, tumor propagation and chemotherapy resistance in triple-negative breast cancer and non-small-cell lung cancer." (PMID 37371594, 2023). "Intriguingly, based on immunostainings for mCD45 cells we revealed an increased initial infiltration of murine leukocytes in ITGB4 KD tumor nodules, which was visible in WT, but not in E-/P-selectin KO mice." (PMID 36932441, 2023). "Furthermore, exogenous TGFβ1 also increased the levels of these three subunits in neutrophils, suggesting that tumor cells up-regulate ITGA6, ITGB1 and ITGB4 in neutrophils through TGFβ1 regulation." (PMID 37056931, 2023). "Of note, the ITGB4 KD alone was by trend accompanied by a higher number of CD3+ cells in the tumor center (p = 0.16), which was not detectable upon combined depletion of ITGB4 and E-/P-selectin KO." (PMID 36932441, 2023). "Moreover, upregulations of ITGB4 and LAMC2 in tumor cells induces EMT properties that promote cancer invasiveness, therapeutic resistance, and metastatic capacity." (PMID 35805064, 2022). "Co-localization of ITGB4 and its ligand laminin 5 was observed at the tumor-stroma interface and an absence of ITGB4 expression correlated with a lack of laminin 5 deposition, demonstrating their co-dependence." (PMID 36076232, 2022). "However, ITGB4 can affect EMT and tumor metastasis via different approaches in various malignancies." (PMID 35305660, 2022).
tumor (continued). "Remarkably, treatment with ITGB4-DC vaccine or ITGB4-BiAb TDLN T cells did not improve 4T1-ITGB4KO tumor growth, strongly suggesting that both of our ITGB4-targeted immunological strategies were ITGB4 specific." (PMID 34504657, 2021). "Furthermore, we investigated the correlation between tumor stage and the expression levels of ITGA11, ITGB4 and ITGB8." (PMID 31875161, 2019). "The qRT-PCR results showed significantly higher expression of ITGB4 in tumor than in adjacent non-tumor tissues (P < 0.01)." (PMID 28084395, 2017). "Real-time PCR and immunohistochemical analyses of tissues from 82 patients with HCC and four HCC cell lines showed higher ITGB4 levels in tumor than in adjacent non-tumor tissues and in HCC than in normal hepatic cells." (PMID 28084395, 2017). "Strikingly, SEC specifically promoted apoptosis by inducing ITGB4 nuclear translocation in a tumor-specific manner, with no side effects in normal cells." (PMID 26918348, 2016). "SEC enhanced ITGB4 phosphorylation by binding to ANXA7 and activating ANXA7 GTPase in tumor cells." (PMID 26918348, 2016). "Finally, we found that down-regulation of Gli reduced the expression of ITGB4 and the phosphorylated FAK, resulting in the inhibition of tumor growth in vivo." (PMID 24533083, 2014). "In addition, the intensity of both ITGB4 and phosphorylation of FAK (Tyr397) was significantly reduced in tumor sections of the GANT61 group compared to the solvent control group." (PMID 24533083, 2014). "Hence, the identified subpopulation of tumor cells exhibiting simultaneous expression of ITGA6 and ITGB4 may serve as a viable target for ongoing therapeutic developments." (PMID 38250718, 2024). "Given the lack of primary tumor growth, a potential cooperative role of E-/P-selectins and ITGB4 for extravasation could principally not be explored in the s.c. xenograft model." (PMID 36932441, 2023). "The CAR T cells induced the production of anti-tumor cytokines and effectively suppressed tumor progression in preclinical models.Recently, the activation of GRP78 ATPase by ZBM-H has been shown to suppress A549 lung cancer cell migration by promoting the degradation of integrin β4 (ITGB4)." (PMID 37605113, 2023). "However, when evaluating the association of ITGB4 with clinicopathological characteristics in OSCC, we found that the ITGB4 expression level is not significantly related to tumor size, lymph node metastasis or pathological grade." (PMID 37371594, 2023). "On the other hand, through protein identification by mass spectrum following PSMA-related immunoprecipitation, we discovered the direct interaction between PSMA and ITGB4, suggesting that ITGB4 may be the downstream target of PSMA to regulate tumor angiogenesis of GBM." (PMID 33748101, 2021). "Moreover, the prognostic signature based on ITGB1, ITGB4, ITGB5 and ITGB6 may facilitate clinicians to identify more aggressive and immunosuppressive tumours and make more individually appropriate therapeutic decisions." (PMID 33073486, 2020). "Only the ITGB4 and ITGA6-expressed CTCs showed differentially expressed genes and the maximum number of increased tumor progression-related genes (26/36) compared to the no integrin CTCs." (PMID 38250718, 2024). "Interestingly, although re‐introducing ITGB4 alone could not support initial DCCs seeding, restoration of ITGB4 in cells expressing ITGB1 increased visible metastatic nodules with a significantly higher tumor burden, as compared to cells expressing ITGB1 alone." (PMID 37828611, 2023).
cancer (111 papers, 2010 to 2026). A tumor composed of atypical neoplastic, often pleomorphic cells that invade other tissues. "In our model, ITGB4 gene (encoding β4) was significantly downregulated in dormant cancer cells in vivo, while ITGB1 (encoding β1) expression remained unaltered." (PMID 37456245, 2023). "Given its prior association with malignant tumor formation, we further validated ITGB4 as a potential KCNF1 target." (PMID 36385523, 2023). "Instead, abrogation or the loss of ITGB4 basal layer expression in cancers is related to the level of malignancy in SCC." (PMID 37371594, 2023). "ITGB4 overexpression has been associated with shortened survival in various cancers, including PDACs." (PMID 35805064, 2022). "Aberrant expression of ITGB4 in lung, breast, and colorectal cancers was associated with poor prognosis." (PMID 34299042, 2021). "Altered localization of the transmembrane receptor ITGB4 is implicated in the progression of carcinoma." (PMID 26918348, 2016). "In fact growing evidence suggests that ITGB4 plays a pivotal role in functions associated with carcinoma progression." (PMID 24533083, 2014). "Among miR-204 gene targets that are potential regulators of cell-matrix interaction and proteolysis, overexpression of APRC1B, CTSC, FAP, MMPs, BMP1, CDH11 and ITGB4 is associated with cancer metastasis and/or poor prognosis." (PMID 20369013, 2010). "ITGB4 is encoded with β4 subunit, which is a laminin receptor that exclusively interacts with α6 subunit and plays a vital role in the biology of infiltrating cancer." (PMID 40386428, 2025). "The identified key proteins, such as SFN, LAMC2, and ITGB4, along with their associated pathways, could serve as potential biomarkers or therapeutic targets for overcoming resistance in this cancer type." (PMID 40959663, 2025). "Increased ITGB4 expression is often associated with cancer invasiveness and angiogenesis." (PMID 38339062, 2024). "Despite the fact that the conclusion regarding the prognostic value of ITGB4 is controversial in different studies on different cancers, we found a high level of ITGB4 to be associated with a relatively prolonged survival in OSCC patients, even though the results were not statistically significant." (PMID 37371594, 2023). "The association of ITGB4 with poor prognosis in many cancers is attributed to the ability of integrin α6β4 to promote malignant behaviours, such as proliferative signaling, the evasion of apoptosis, tissue invasion and metastasis, and the induction of angiogenesis." (PMID 28084395, 2017). "The ITGB4‐encoded integrin β4 subunit, which is the laminin receptor, exclusively associates with the α6 subunit and may play a key role in the biology of infiltrating cancer." (PMID 34414684, 2021). "Most importantly, the previously cancer‐associated UEA lectin was consistently associated with the highest S/B ratios, ITGB4–UEA being the best antibody–lectin pair." (PMID 40287842, 2025). "First, we performed a pan cancer analysis of ITGB4 expression in The Cancer Genome Atlas (TCGA) dataset." (PMID 38172503, 2024). "By deciphering these mechanisms, we sought to provide valuable insights for further research exploring the impact of ITGB4 on cancer metastasis." (PMID 39169946, 2024). "To verify this idea, we first analyzed the expression of CAVI, ITGA6, and ITGB4 in different BC cell lines in The Cancer Cell Line Encyclopedia database." (PMID 39494337, 2024). "Many TME-related genes (such as VEGFA, MMP14, CCND1, MAP2K1, SLC2A1) and actin cytoskeleton-associated genes (such as ITGB4, ITGA6, ACTG1, VCL) were downregulated, suggesting a less favorable TME and an altered cytoskeleton network in ISO-treated cancer cells." (PMID 38339062, 2024). "ITGB4 is widely recognized as a molecule with both prognostic and predictive value in cancer patients." (PMID 39169946, 2024). "ITGB4 disrupts cell adhesion and basement membrane integrity, thereby promoting cancer progression and metastasis." (PMID 38409471, 2024).